CRP (C-reactive protein)
Diseases named in the same sentence as CRP in open-access papers (continued):
Sharing a sentence is not in itself a finding about the gene and the disease.
atherosclerosis (continued). "For example, in older people with atherosclerosis, CRP levels are elevated, reflecting the degree of atherosclerosis." (PMID 40242549, 2025). "The potential underlying mechanism linking CRP and CAD likely involves inflammatory processes, a crucial factor in atherosclerosis, and consequently, CAD advancement." (PMID 40922854, 2025). "CRP potentially fosters monocyte attachment and movement within vessel walls, a key early phase of atherosclerosis." (PMID 40933377, 2025). "CRP contributes to the promotion of atherosclerosis by direct pathways involving activation of the complement system, induction of apoptosis, and ED." (PMID 40283183, 2025). "Concerning this, in a rabbit model of atherosclerosis, topical application of RvE1 attenuated atherosclerotic plaque formation and lowered C-reactive protein (CRP) levels." (PMID 38612996, 2024). "The study revealed a notable association between hs-CRP levels and CAD diagnosis, emphasizing the role of inflammation in atherosclerosis." (PMID 38590494, 2024). "Accordingly, high-sensitivity C-reactive protein (hs-CRP) is a predictive inflammatory biomarker regarded as a crucial indicator of atherosclerosis development." (PMID 39141186, 2024). "Recognizing the critical role of inflammation in atherosclerosis, clinicians frequently utilize markers reflecting inflammation, such as CRP and albumin." (PMID 38673005, 2024). "Except for being a part of an immune reaction during infection or extensive tissue injury, several papers demonstrated the important role of CRP as a biomarker of various cardiovascular pathologies, including atherosclerosis and ischemic heart disease." (PMID 38627621, 2024). "Elevated CRP levels in patients with periodontitis indicate systemic inflammation and disease severity, contributing to endothelial dysfunction, atherosclerosis, and increased risks of cardiovascular events and mortality." (PMID 39453923, 2024). "Our results suggest that CRP is the most important risk factor that connects ABI and carotid artery stenosis, which are important non-invasive indicators of generalized atherosclerosis in T2DM." (PMID 38248862, 2024). "Our finding that platelet counts show the highest correlation with those of leukocytes and CRP levels aligns with their role in inflammation and atherosclerosis." (PMID 38255379, 2024). "Univariate and multivariate logistic regression to identify associations between hs-CRP, IL-17, TNF-α, and atherosclerosis in psoriasis patients." (PMID 39104857, 2024). "Specifically, patients with high serum CRP levels not only had larger AAA diameters but also exhibited strong CRP deposition at the atherosclerosis-aortic wall interface and within the intima and media of resected aortic specimens." (PMID 39737187, 2024). "The inflammatory nature of atherosclerosis is evidenced by the correlation of inflammatory markers, especially C-reactive protein (CRP), with the onset and progression of the disease." (PMID 39599480, 2024). "CRP plays a crucial role in all stages of atherosclerosis, exacerbating endothelial dysfunction and promoting plaque formation and thrombogenesis." (PMID 39595081, 2024). "CRP has prognostic value based on mechanism of inflammation and oxidative stress which occurs in atherosclerosis; however, other biomarkers like NT-proBNP or OxLDL were more sensitive and are associated with better prediction." (PMID 39459566, 2024). "Some studies have reported that CRP is increased in patients with atherosclerosis and that this is related to prognosis." (PMID 39687453, 2024). "Vitamin D decreases inflammatory markers (C-reactive protein, Interleukin 10) and oxidative stress markers (free radicals, nitric oxide), thus influencing atherosclerosis." (PMID 38592202, 2024).
atherosclerosis (continued). "The elevated CRP levels in individuals with plantar fasciitis suggest that chronic heel pain may not merely be a localized issue but could also reflect broader systemic inflammation, which is a recognized risk factor for atherosclerosis and cardiovascular events." (PMID 38983990, 2024). "Several studies connected elevated concentrations of CRP with atherosclerosis, such as coronary heart disease and stroke." (PMID 38248862, 2024). "Vascular inflammation plays a crucial role in the pathogenesis of atherosclerosis, and it is often assessed using biomarkers such as high-sensitivity C-reactive protein (hs-CRP)." (PMID 39286672, 2024). "Among the biomarkers of CVD, C-reactive protein (CRP) serves as an acute inflammatory biomarker and is used in predicting the risk of atherosclerosis." (PMID 38921462, 2024). "Subsequent study ought to include supplementary biomarkers, including C-reactive protein (CRP), homocysteine, and fibrinogen, to enhance the understanding of the inflammatory and thrombotic mechanisms implicated in atherosclerosis." (PMID 39459504, 2024). "CRP was shown to be the most studied biomarker of cardiovascular pathologies, particularly atherosclerosis and ischemic heart diseases." (PMID 38627621, 2024). "CRP is one of multiple markers of inflammation seen in atherosclerosis and other cardiovascular diseases, which involves low-grade systemic inflammation." (PMID 38673472, 2024). "This study aimed to measure the associations between inflammatory biomarkers, IL-17A, TNF-α, hs-CRP, and atherosclerosis in patients with psoriasis." (PMID 39104857, 2024). "Other indices will be arrhythmia, blood pressure variability, and biomarkers of atherosclerosis, such as blood lipids, hypersensitive C-reactive protein (hs-CRP), homocysteine, and total bilirubin." (PMID 38195481, 2024). "As GDF-15 expression on ECs has been shown to be induced by C-reactive protein (CRP) and atherosclerosis is chronic inflammation, future studies should assess CRP levels to confirm the association between GDF-15 and the degree of atherosclerosis." (PMID 38396781, 2024). "The high-sensitivity C-reactive protein (hs-CRP) level is a measure of the body's inflammatory response to atherosclerosis and serves as a peripheral marker of inflammation." (PMID 39247228, 2024). "This is an unusual finding, since Cpn infection is recognized as having a pro-inflammatory effect in atherosclerosis, alongside the rise in CRP, fibrinogen and other markers of inflammation." (PMID 39599480, 2024). "This study aimed to measure the associations between different inflammatory factors, namely interleukin (IL)-17A, tumor necrosis factor (TNF)-α, and high-sensitivity C-reactive protein (hs-CRP), and atherosclerosis in patients with psoriasis vulgaris." (PMID 39104857, 2024). "Although CRP is produced at higher levels in the liver in response to infections and high-degree inflammation, there is also a low-grade inflammation with CRP released from the vascular endothelium thought to mirror atherosclerosis." (PMID 38732147, 2024). "Elevated CRP levels may serve as an indirect indicator of endothelial cell impairment, activation of inflammatory cytokines, vascular damage, and the predominant thrombotic conditions, all of which are intricately linked to the development and progression of atherosclerosis." (PMID 38816852, 2024). "CRP contributes to atherosclerosis by promoting endothelial dysfunction, plaque formation, and rupture." (PMID 39453923, 2024). "CRP has a significant role in the pathogenesis of the development and progression of atherosclerosis." (PMID 38248862, 2024). "The observed effects of statin on CIMT and CRP further suggest that statin not only offers lipid-lowering properties but has additional effects in reducing inflammation and early atherosclerosis." (PMID 39330333, 2024).
atherosclerosis (continued). "IL-6 induces the acute phase response, leading to increased levels of CRP and fibrinogen and monocyte activation, the activated monocytes deposit fibrinogen in the vessel wall, leading to atherosclerosis." (PMID 38988836, 2024). "The mechanism involves bacteria from the mouth entering the bloodstream, triggering immune responses that elevate systemic inflammation markers, such as C-reactive protein (CRP) and interleukin-6 (IL-6), both of which are also linked to atherosclerosis." (PMID 39677218, 2024). "CRP knockout animals have greater levels of autoimmune inflammation, atherosclerosis and liver disease progression." (PMID 37048104, 2023). "Other studies also support a direct role for CRP in the development and/orprogression of atherosclerosis via the blocking of endothelial regeneration." (PMID 39077585, 2023). "Another action is the indirect reduction of the activation of IL-1β and downstream in IL-6 and CRP, which are well-known mediators that activate macrophages and propagate atherosclerosis." (PMID 37374202, 2023). "CRP is an acute reactive protein and inflammatory marker, which can accelerate the formation and progression of atherosclerosis, thus aggravating the plaque load." (PMID 37025371, 2023). "In vascular disease, atherosclerosis is related to an inflammatory process (manifested by elevated CRP levels), and in advanced atherosclerotic plaques, AlkP expression are increased." (PMID 37867513, 2023). "In summary, it appears that CRP impairs normal endothelial function andregeneration capacity, thereby leading to endothelial dysfunction and theinitiation of atherosclerosis." (PMID 39077585, 2023). "Some of them, such as TNF-α and C-reactive protein, are known to be mediators of atherosclerosis and endothelial alterations by damaging vascular functionality and reducing the nitric oxide (NO) availability." (PMID 38001946, 2023). "Preclinical studies in murine models have shown that IL-6 promotes atherosclerosis and possibly plaque vulnerability and that injection of IL-6 results in increased CRP, TNF-α, and fibrinogen levels." (PMID 37629526, 2023). "C-reactive protein contributed to atherosclerosis progression by promoting platelet activation and modulating inflammatory response and immune response." (PMID 37803341, 2023). "Current data suggests that CRP is more than just abiomarker of atherosclerosis and cardiovascular disease." (PMID 39077585, 2023). "CRP is an acute-phase protein synthesized in the liver during infection and inflammation, and its role in the course of atherosclerosis, which is an inflammatory process, has been shown in numerous studies." (PMID 36874319, 2023). "While it seems clear that CRP should be used as a therapeutictarget for atherosclerosis and cardiovascular disease, questions remain about howthis can be achieved." (PMID 39077585, 2023). "In this context, patients with decreased preprocedural GNRI values and elevated CRP levels were considered to have advanced atherosclerosis and poor prognosis in the present study." (PMID 38202133, 2023). "CRP, one of the important predictors of cardiovascular events, is closely related to the occurrence of atherosclerosis." (PMID 37790809, 2023). "Canakinumab reduces the recurrence of cardiovascular disorders (MI and angina) in patients with atherosclerosis and MI accompanied by decreased C-reactive protein (CRP)." (PMID 38270118, 2023). "While this favors the transformation ofinnate immune recognition by CRP into immediate adaptive immune responses, thereis also the potential for autoimmune activity in atherosclerosis." (PMID 39077585, 2023). "A significant difference was also registered between patients with ulcerative colitis and patients with atherosclerosis compared to healthy patients, confirming that CRP is a good marker of chronic inflammation." (PMID 36984554, 2023).
atherosclerosis (continued). "In our study, the highest CRP values were in patients with ulcerative colitis and patients with ulcerative colitis and atherosclerosis, which was expected because CRP is a positive reactant of acute inflammation." (PMID 36984554, 2023). "Previous studies have shown that CRP can promote atherosclerosis, blood stagnation, and plaque formation." (PMID 37168805, 2023). "Here, we show that the majority of the considered cholesterol-containing lipoprotein and apolipoproteins affect measures of atherosclerosis, blood pressure, C-reactive protein (CRP), and CHD." (PMID 36670186, 2023). "In this sense, it has been described that serum levels of miR‐199a‐3p negatively correlated with the carotid intima‐media thickness and C reactive protein in patients with atherosclerosis." (PMID 37605307, 2023). "CRP plays a role in atherosclerosis via enhanced IL-8 production and an increased expression of IL-8 mRNA." (PMID 38138192, 2023). "Upstream movement of the inflammatory cascade from CRP to IL-6 to IL-1 offers new therapeutic opportunities for atherosclerosis protection." (PMID 36873405, 2023). "Circulating inflammatory markers such as interleukin-6 (IL-6) and C-reactive protein (CRP) are closely related with endothelial dysfunction and atherosclerosis." (PMID 37831667, 2023). "Higher levels of interleukin-6 and CRP are positively correlated with atherosclerosis in SSc patients." (PMID 38066767, 2023). "The path of atherosclerosis is significantly stimulated via way of means of inflammation, and the high-sensitivity C-reactive protein (CRP) level has been recognized as a predictor of cardiovascular risk." (PMID 37123792, 2023). "The basis of the relationship between CRP and atherosclerosis is the CRP’s potential to directly modulate the production of endothelium-derived vasoactive factors." (PMID 37841398, 2023). "CRP, LBP, and OPG are probably only markers of ongoing process of atherosclerosis that reflect vitamin D deficiency." (PMID 37623831, 2023). "Only one SNP was found in the atherosclerosis-CRP outcome GWAS; thus, the Wald ratio MR method was used to determine the causal estimates." (PMID 37298077, 2023). "Atherosclerosis is one of the leading causes of AMI, and inflammatory mediators such as IL-6, TNFα, and CRP are potential biomarkers for the diagnosis of AMI in patients with angina." (PMID 36672669, 2023). "CRP and IL-6, as markers of inflammation, have been widely studied and described as factors in the development of atherosclerosis." (PMID 37509461, 2023). "Among thousands of cytokines, NOD-, LRR-, and pyrin domain-containing protein 3 (NLRP3), C-reactive protein (CRP), IL-1, and IL-6 were involved in atherosclerosis pathogenesis." (PMID 37555019, 2023). "CRP is generated by the liver when there is inflammation, and atherosclerosis is an inflammatory cardiovascular disease." (PMID 37860004, 2023). "CRP also has prognostic value in (subclinical) atherosclerosis, but several studies have detected this condition in parallel with several other diseases." (PMID 37873776, 2023). "A multicenter study from Spain found that CRP > 3 mg/L and ESR at the time of diagnosis were significantly associated with CIMT, a surrogate marker of atherosclerosis." (PMID 37109438, 2023). "A putative function for CRP in atherosclerosis is suggested by the co-localization of CRP and low-density lipoproteins (LDL) at atherosclerotic lesions." (PMID 37860004, 2023). "Serum concentrations of C-reactive protein (CRP), interleukin-6 (IL-6), and LDL are highly correlated with clinical symptoms of atherosclerosis and an increased risk of death from cardiovascular disease." (PMID 37570897, 2023). "Since patients with T2D have been shown to have higher CRP levels, this SNP should be excluded from the atherosclerosis-CRP analysis, making the relationship between atherosclerosis and CRP unreliable." (PMID 37298077, 2023).
atherosclerosis (continued). "On the other hand, CRP appears not to have a causal role in atherosclerosis.Although it is present in all stages of atherosclerotic plaque, CRP is considereda mediator of atherosclerosis." (PMID 39076864, 2023). "Effects are seen on measures of atherosclerosis, blood pressure, c-reactive protein, coronary heart disease, heart failure, Alzheimer’s disease, type 2 diabetes and inflammatory bowel disease." (PMID 36670186, 2023). "We analyzed the causal associations between CRP and the risk of the most prevalent CVD outcomes: myocardial infarction, coronary artery disease, heart failure, and atherosclerosis." (PMID 37298077, 2023). "Elevated levels of C-reactive protein (CRP), interleukin-1 (IL-1) and interleukin-6 (IL-6) are associated with atherosclerosis and its complications, including plaque initiation, progression and rupture." (PMID 36830690, 2023). "C‐reactive protein (CRP) is a sensitive and stable marker of systemic inflammation and has been postulated to predict the extent of atherosclerosis." (PMID 37125237, 2023). "CRP contributes to all phases of atherosclerosis, exerts anti‐inflammatory effects, and maintains balance in the inflammatory process." (PMID 37125237, 2023). "CRP is an acute-phase protein produced in the liver, and also reflects chronic inflammation, including atherosclerosis burden." (PMID 36836211, 2023). "Elevated concentrations of both CRP and SAA have been suggested to identify atherosclerosis and thus risk of CVD." (PMID 35819531, 2022). "At a first glance, discussing CRP and atherosclerosis in conjunction with phylogeny and “lower” organisms seems to be absurd." (PMID 35402541, 2022). "Regarding the differential development of atherosclerosis and CAS, smoking and CRP have been demonstrated to be the 2 important risk factors for both diseases." (PMID 35096275, 2022). "Plasma CRP levels can reliably predict the prognosis of atherosclerosis, heart failure, and other CVD, even in otherwise asymptomatic individuals." (PMID 36503487, 2022). "Increased circulating levels of IL-1β, IL-6 and C- reactive protein (CRP) also promote atherosclerosis, independently of circulating levels of LDL particles." (PMID 35757738, 2022). "Several studies testified that CRP is a vital factor in cardiovascular diseases, such as atherosclerosis, myocardial infarction, and stroke in OSA." (PMID 36363559, 2022). "As part of the acute phase response, IL-6 increases CRP, fibrinogen, and plasminogen activator inhibitor levels, which are closely related to atherosclerosis." (PMID 36082127, 2022). "Rising plasma levels of TNF-α is associated with IL-6 and CRP in elderly people as well; TNF-α is correlated to atherosclerosis and Alzheimer’s in people over 100 years old78." (PMID 36496428, 2022). "CRP has also been shown to increase sICAM-1 and sVCAM-1 concentrations in endothelial cells in the presence of serum, suggesting that CRP concentrations affect other inflammatory components and the progression of atherosclerosis." (PMID 35881632, 2022). "Increased incidence of atherosclerosis and CVD events in RA patients are associated with anti-CCP and CRP levels." (PMID 36249997, 2022). "High levels of effort, over-commitment and effort–reward imbalance at work increase CRP levels significantly in both sexes and link job stress and stress-related diseases such as atherosclerosis." (PMID 35453318, 2022). "A rise in C-reactive protein increases the serum levelsof atherogenic biomolecules and induces development of atherosclerosis." (PMID 39077184, 2022). "Inflammation plays a critical role in atherosclerosis and the inflammatory marker CRP has been shown to have a strong predictive power for CV events." (PMID 35407506, 2022). "LncRNA DANCR was highly expressed in the serum samples of patients with atherosclerosis and was positively associated with LDL-C, Hcy, and CRP levels." (PMID 35235755, 2022).